CD4 (CD4 molecule)
Diseases named in the same sentence as CD4 in open-access papers (continued):
Sharing a sentence is not in itself a finding about the gene and the disease.
ZIKV infection (continued). "For instance, CD4+ and CD8+ T cells primed against DENV are capable of protecting mice against ZIKV infection." (PMID 36926332, 2023). "In the HLA-transgenic mouse model, vaccination with cross-reactive CD4+ T cell epitopes of both DENV and ZIKV significantly reduced ZIKV infection, indicating the protective role of CD4+ T cells in the cross-reactivity." (PMID 35746683, 2022). "Although, conventionally, CD8+ is the major T cell mediating cytotoxic reactions against infected cells, recent research indicates that CD4+ T cells also exert similar cytotoxic effects as CD8+ T cells during DENV and ZIKV infection." (PMID 36159640, 2022). "Both CD4+ and CD8+ cells are activated in many flavivirus infections, including ZIKV infection, which can exert inflammatory responses to the host." (PMID 35215836, 2022). "As observed in humans, DENV antibodies have been shown to increase CD4+ and CD8+ T-cell responses during ZIKV infections." (PMID 34745123, 2021). "Others have shown that Granzyme B levels in CD4+ and CD8+ T cells peaked between 7 and 10 days post-ZIKV infection." (PMID 32463814, 2020). "To characterize immune responses to ZIKV, here we examine transcriptional signatures of CD4 T, CD8 T, B, and NK cells, monocytes, myeloid dendritic cells (mDCs), and plasmacytoid dendritic cells (pDCs) from three individuals with ZIKV infection." (PMID 32415086, 2020). "Collectively, these results demonstrate that, at the peak of the T cell response, ZIKV infection induces expansion of Ab-promoting TFH cells and IL-10-producing CD4+ T cells, but suppresses the population of Treg cells." (PMID 30677097, 2019). "In humans, preexisting DENV immunity has been shown to boost CD4+ and CD8+ T-cell responses during Zika virus infections." (PMID 31075077, 2019). "In all, these studies demonstrate the importance of robust CD4 and CD8 T cell responses during ZIKV infection." (PMID 31382545, 2019). "In sorted Tfh cells (CD4+CD44highCD62LlowGFPhighPD-1high), 74% of cells produced IFN-γ in immune-modulated ZIKV infection; whereas only 24% of them in ZIKV envelope protein immunization group did so." (PMID 31455769, 2019). "Since ZIKV infection leads to a rapid expansion in the frequency of TFH cells, we next investigated the requirement for CD4+ T cells in generating ZIKV-specific Abs during primary infection." (PMID 30677097, 2019). "In this report, we used mouse models of systemic and genital mucosal infection with ZIKV to evaluate the role of CD4+ T cells in regulating antiviral humoral and CD8+ T cell responses and in controlling ZIKV infection." (PMID 30677097, 2019). "The results of these studies confirmed the necessity of CD8+ T cells for the control of ZIKV infection in Ifnar1−/− mice, but point to a different role for CD8+ T cells in the control of ZIKV as compared to what we had previously observed with CD4+T cells." (PMID 31379867, 2019). "DENV and ZIKV infections and DENV/ZIKV coinfections similarly induced expression of CCR5, CX3CR1, and CXCR3 on CD4 and CD8 T cells." (PMID 29282904, 2018). "Frequency of cytokine‐producing T CD4+ and CD8+ are differentially regulated in DENV, ZIKV, and DENV/ZIKV infection." (PMID 29282904, 2018). "Collectively, these results show a key role for CD8+ T cells, with a more limited requirement for CD4+ T cells, in DENV-immune-mediated cross-protection of ZIKV infection in maternal tissues from Ifnar1−/− mice." (PMID 30072692, 2018). "Even without specific in vitro antigenic stimulation, DENV, ZIKV, and DENV/ZIKV infections induced expression of CCR5, CX3CR1, and CXCR3 on CD4+ and CD8+ T cells, indicating an activated status of these cells." (PMID 29282904, 2018). "In terms of total blood profiling, viremic patients experiencing moderate symptoms of ZIKV infection had reduced numbers of DNT cells, CD4+ T cells, and CD8+ T cells." (PMID 29672707, 2018).
ZIKV infection (continued). "We surmised that as the Ifnar1-/- mice were more sensitive to ZIKV infection than the immune competent C57BL/6J, and would therefore have higher antigen loads in the Ifnar1-/- mice resulting in stronger ZIKV-specific CD4+T cell responses." (PMID 30212537, 2018). "Variables added to the model were: maternal CD4+ count, maternal HIV viral load, use of ARVs before pregnancy, and maternal ZIKV infection." (PMID 29979796, 2018). "While several studies have shown the CD4+T cells responding to ZIKV infection can produce cytokines other studies point to a more dominant role of CD8+T cells in controlling ZIKV infection." (PMID 30212537, 2018). "ZIKV infection was characterized by a CD4 T cell differentiation toward effector cells and by a lower frequency of IFN-γ producing CD4 T cells." (PMID 28740159, 2017). "We found that ZIKV infection induced a significant activation of CD8 and CD4 T-cells, confirming recent data obtained in mice." (PMID 28740159, 2017). "The impact of ZIKV infection on T-cell activation was evaluated by analyzing the expression of activation markers CD38 and HLA-DR on CD8, CD4 and on DN T-cells." (PMID 28740159, 2017). "Immune profiling of the memory CD4+ and CD8+ T-cell responses in the naïve and DENV-immune macaques revealed no defects in the ability of the DENV-immune cohort to respond to ZIKV infection." (PMID 28643775, 2017). "In summary, this study shows for the first time the activation of both CD8 and CD4 T-cell subsets, a reduction of IFN-γ producing CD4 T-cells and a prolific expansion of effector Vδ2 T-cells during acute ZIKV infection." (PMID 28740159, 2017). "During the acute phase of ZIKV infection, the number of specific innate and adaptive cell types temporarily increased, including intermediate CD14+CD16+ monocytes, CD69 + NK, HLA‐DR+CD38+ non‐naïve CD8+ T cells, Th1 CD4+ T cells, and Tbet+ plasma cells." (PMID 41556482, 2026). "This denotes that a lack of CD4+ T cells has an effect on the Ab repertoire that leads to an increase in ZIKV infection compared to undepleted animals and to previously reported naïve animals." (PMID 41295476, 2025). "It is important, however, to note that in these transgenic mice, the class II molecules are of murine origin, which highlights the limit of our study in that both CD4+ and CD8+ T cells have been shown to mediate protective immunity to DENV and ZIKV infection in humans." (PMID 39418312, 2024). "Furthermore, the CD4+ TEMRA cells displayed higher proportions of cells co-expressing Ki-67 and the immune checkpoint markers CTLA-4 and PD1, at this early stage of the ZIKV infection." (PMID 38722858, 2024). "Overall, an ex vivo spontaneous IFN-γ production was co-detected together with a percentage STAT-5 signaling in memory or effector-memory CD4+ and CD8+ T cells that co-displayed activation markers in the earliest samples from patients with acute ZIKV infection and over two-week interval." (PMID 38722858, 2024). "In our mass cytometry study, we observed a significant proportion of CD4+ PD1+ T cells in all patients during early acute ZIKV infection compared to HD, regardless of their DENV viremic or serological status." (PMID 38722858, 2024). "Indeed, it has been shown that induction of ZIKV-specific CD4+/IFN-γ+ T cells is also critical to B cell activation, antibody maturation and protection against ZIKV infection." (PMID 37112733, 2023). "Thus, there was variability in CD4+ T cell phenotypes in response to in vitro stimulation with ZIKV MP among adult women and children with a history of ZIKV infection." (PMID 35215843, 2022). "During ZIKV infection, humans, nonhuman primates, and mice generated virus-specific CD4 + and CD8 + T cells." (PMID 35027643, 2022). "aegypti saliva protein reported to enhance ZIKV infection in humans but that was not identified in our pull-down assay moderately interacts with CD4 in the ELISA assay." (PMID 36070318, 2022).
ZIKV infection (continued). "Similarly, a case report from Florida identified NS2-specific CD4 T cells and envelope-specific CD8 T cells in a returning traveler with ZIKV infection." (PMID 31382545, 2019). "Although CD4+ T cells are not necessary for the control of primary ZIKV infection via the intravenous route, CD4+ T cells can confer protection against lethal intravaginal ZIKV challenge." (PMID 30677097, 2019). "Thus, immunocompetent mouse models represent a very useful tool for characterizing and understanding the CD4 and CD8 T cell responses to ZIKV infection." (PMID 31382545, 2019). "Finally, in an Italian cohort, ZIKV infection activated both CD4 and CD8 T cells, but only CD4 T cells acquired an effector memory phenotype when compared to CD4 T cells from healthy controls." (PMID 31382545, 2019). "Another group found that while prior DENV exposure had no impact on the CD4 T cell response to ZIKV infection, patients in the acute phase of ZIKV infection had more IFN-γ+ CD8 T cells after restimulation with ZIKV-derived peptides." (PMID 31382545, 2019). "However, DENV/ZIKV coinfection decreased the ability of CD4+ T cells to produce IFNγ+, TNF+, TNF+ IFNγ+, and TNF+ IL2+, compared to DENV and ZIKV infections." (PMID 29282904, 2018). "While the CD4+T cell depletion experiments demonstrate that the CD4+T cells are necessary for protection, these results indicate that ZIKV specific CD4+T cells are sufficient to protect against lethal ZIKV infection." (PMID 30212537, 2018). "Taken together, these results establish that ZIKV infection induces a prototypical Th1 CD4+ T cell response, without inducing substantial Th2 or Th17 responses." (PMID 28231312, 2017). "In contrast to the ZIKV infection data presented here, secondary DENV infections have revealed highly serotype-cross-reactive CD4+ and CD8+ T cells, which have been hypothesized to contribute to disease severity." (PMID 28771605, 2017). "Nevertheless CD4+ T cells from most of the naïve and DENV-immune macaques were able to induce ZIKV specific CD4+ T responses after ZIKV infection suggesting that, similar to CD8+ T cells, a prior DENV infection did not dampen the cellular immune response to ZIKV." (PMID 28643775, 2017). "Hassert and coworkers used a mouse model of ZIKV infection to demonstrate that ZIKV epitope-specific CD4+T cells induced protective cell-mediated immune responses with Th1 cells secreting type 2 IFN and TNFα, being the predominant subset of effector CD4+T cells." (PMID 35736984, 2022). "For example, uniquely in acute ZIKV infection, we observed negative correlations between the frequency of ABCs and CD4+ regulatory T cells (Tregs) (r = −0.86, p_adj = 0.002) and between CD69+ CD56dim NK cells and Helios+ Vδ2- γδ T cells (r = −0.77, p_adj = 0.03)." (PMID 35584677, 2022). "Thus, after in vitro stimulation with ZIKV MP, our data suggest that IL-17-producing CD4+ T cell subsets appeared not to be primed through acute ZIKV infection." (PMID 35215843, 2022). "The correlations unique to acute ZIKV infection (e.g., positive correlations in the proportion of CD38+ pDCs and CD38+ Th1 CD4+ T cells, or between CD40+ cDCs and Ki-67+ DN B cells) may reflect interactions that are essential to mount a productive antiviral immune response." (PMID 35584677, 2022). "However, ZIKV MP-responding IL-17+ IFN-γ+-coproducing CD4+ T cell subsets were primed mainly in the mothers and children, but not in the women with histories of ZIKV infection." (PMID 35215843, 2022). "However, surprisingly, we detected an increase in IL-17A+ IFN-γ+-producing CD4+ T cells (Th1Th17 cells) in the mothers and children, but not in the women with a history of ZIKV infection." (PMID 35215843, 2022). "Additionally, memory CD4+ T cells contributed to viral clearance in mice after primary, but not secondary, intravenous ZIKV infection." (PMID 30677097, 2019).
ZIKV infection (continued). "Similarly, another study observed that CD4+ T cells were not necessary to control secondary subcutaneous ZIKV infection of mice." (PMID 30677097, 2019). "In addition, infiltrates of CD4+ and CD8+ lymphocytes were detected in the brains of infected mice, indicating that both helper and cytotoxic lymphocytes, respectively, infiltrate the mouse brain following ZIKV infection." (PMID 31488835, 2019). "Depletion of CD4+ T cells impaired the generation of neutralizing Abs during the peak of the T cell response following IVag, but not intravenous, ZIKV infection, which is probably due to the different times at which the T cell response peaks post-infection via the two routes." (PMID 30677097, 2019). "Measurement of viral particles in the serum, brain, and testes revealed almost complete eradication of virus in ZIKV-primed mice compared with mock-primed mice on day 3 after secondary ZIKV infection, with no apparent difference between anti-CD4-treated and control Ab-treated mice." (PMID 30677097, 2019). "It is conceivable that in ZIKV infection the role of CD4+ T cells could range from nonessential as in DENV to multifaceted as in WNV." (PMID 30087337, 2018). "Unlikely DENV infections, in which CD4+ T cells target structural proteins and CD8+ T cells target mainly nonstructural proteins, in ZIKV infection, both CD4+ and CD8+ T cells target structural proteins." (PMID 32878023, 2020). "Indeed, CD8+ T cells from patients with confirmed ZIKV infection had been shown to mainly recognize the nonstructural proteins NS3, NS5, and NS4B, whereas CD4+ T cells primarily recognize the capsid and envelope structural proteins." (PMID 38722858, 2024). "Changes in the number of neutrophils (CD45+CD16+), monocytes (CD14+), B cells (CD19+), T cells (CD3+CD4+, CD3+CD8+), double-negative (CD3+CD4-CD8-) T (DNT) cells, NK cells (CD56+ and CD56hi) NK T cells (CD56+CD3+), and CD14+CD56+ cells during acute ZIKV infection were profiled." (PMID 29672707, 2018).
dermatitis (72 papers, 2007 to 2025). An inflammatory process affecting the skin. "While the pathogenesis of the secondary skin lesions (including opportunistic infections and malignant skin cancers) is associated with decreased CD4 counts, the origin of the primary cutaneous disorders is still being investigated." (PMID 32850174, 2020). "In this study, we demonstrated that Nfkbiz-deficient (Nfkbiz−/−) mice with atopic-like dermatitis have elevated serum IgE Abs and drastically increased numbers of IL-17A-secreting CD4+ T cells in skin." (PMID 28740238, 2017). "However, IMQ induces strain dependent responses, at least in dermatitis, and CD4+ T cell-associated gene expression was weaker in the B6 background." (PMID 32655553, 2020). "The pleiotropic mechanism of IL-16 may suggest its role in the pathogenesis of cutaneous disorders closely associated with infiltration of CD4+ T-cells." (PMID 27788245, 2016). "For example, during Staphylococcus aureus exposure, IL-36α secretion from keratinocytes induces skin inflammation characterized by the infiltration of γδT cells, CD4+ T cells, and neutrophils via MyD88 signaling." (PMID 40563457, 2025). "EA exerts therapeutic effects on persistent itch and skin inflammation in AD mice by activating CB2R, thereby inhibiting mast cell and CD4 + T cell proliferation and the expression of associated inflammatory factors, as well as downstream ERK phosphorylation." (PMID 40420206, 2025). "In conclusion, the insight from our study into the relevance of ICOS+CD4+ T cells is potentially meaningful for a better understanding of irAE pathogenesis beyond lung toxicity, including skin disorders." (PMID 40198121, 2025). "Consistent with observations in rosacea patients, we found a marked increase in infiltrating CD4+ T cells in the skin lesions of young mice with LL37‐induced rosacea‐like dermatitis, whereas fewer CD4+ T cells were infiltrated in aged mice." (PMID 39692542, 2024). "Nonetheless, heightened skin inflammation or infection leads to augmented recruitment of CD4+T cells to the skin and their retention in the dermis." (PMID 38779662, 2024). "All of the Btla−/− CD4 SP T cell recipient mice had a hunched appearance, piloerection, diarrhoea and some had dermatitis." (PMID 39471840, 2024). "For instance, biopsy samples from patients with dermatitis show a high presence of CD4+, CD8+ T cells, Th1 cells, autoantibodies, complement proteins and immunoglobulin (Ig)G and IgE." (PMID 39247203, 2024). "The model demonstrates dermatitis, epidermal hyperplasia, and spongiform disease with a predominant Th2 response and increased CD4 and CD8 cell infiltration." (PMID 36993982, 2023). "OVA/SEB mice: This model features Th2-type skin inflammation, increased CD4+ T and CD8+ T cell infiltration, and markedly increased Th-related chemokines in exposed skin." (PMID 36993982, 2023). "Studies have demonstrated that the MC903-induced chronic inflammation is CD4+ T cell-dependent, and Tregs are involved in the skin inflammation and play a regulatory role." (PMID 34868040, 2021). "To clarify the underlying mechanism of HB-based immunomodulation, we analyzed mouse splenocytes in different treatment groups using multi-color flow cytometry to characterize the phenotype of CD4+ T cell subsets in DNCB-induced skin inflammation." (PMID 34531749, 2021). "Several reports suggested that in superficial perivascular dermatitis induced by ICIs, there were increased numbers of CD4+ lymphocytes compared with CD8+ lymphocytes, as well as regulatory T cells." (PMID 33673164, 2021). "This evidence suggests that HB effectively mitigates skin inflammation in mice with DNCB-induced AD by restoring the balance of the CD4+ T cell response." (PMID 34531749, 2021). "Dermatitis is typically associated with both skin-produced cytokines (e.g., IL-33, -17C, and TSLP), and a skewing of CD4+ T cells into T helper 2 (Th2) and their associated cytokines (e.g., IL-4,-5,-13,)." (PMID 33017398, 2020).